EGFR (epidermal growth factor receptor)
Diseases named in the same sentence as EGFR in open-access papers (continued):
Sharing a sentence is not in itself a finding about the gene and the disease.
cancer (continued). "The activated EGFR induced by EGF could translocate into the nucleus, and function as a co-transcription factor and kinase to promote proliferation, invasion and survival of cancer cells." (PMID 30971297, 2019). "By eliminating the expression of this receptor in cancer cells, due to apoptotic mechanisms, a decrease in the number of these cells has been reported and it is also known that in tumor cells the application of the siRNA TAC1R method decreased the levels of p-EGFR, p-Akt and p-ERK." (PMID 31466222, 2019). "Diarrhea, a common side effect of many cancer treatments, including chemotherapeutic agents, targeted therapies, and pelvic radiotherapy, is one of the most common adverse events reported during treatment with a TKI, and can be dose-limiting for TKIs that block EGFR signaling." (PMID 30671765, 2019). "Thus, the ability of SEMA3C to simultaneously transactivate multiple RTKs such as EGFR, HER2 and MET could facilitate the switch of primary dependency of cancer growth from one RTK pathway to another." (PMID 30759745, 2019). "In this manuscript, we use the same method to deliver PTX to cancer cells: NLC is the PTX carrier with the surface modified with PEG and AR at the distal end of PEG (A-P-NLC) to achieve the active targeting effect towards the EGFR overexpressed NCI-H1299 cells." (PMID 30880491, 2019). "Thus, altered expression of EGFR regulators and the resultant changes in ERK activity dynamics might be prevalent in these cancers." (PMID 30974867, 2019). "Moreover, the combined inhibition of Pyk2 and EGFR signaling may be a rescue therapy when the combination treatments of FAK inhibitors and EGFR signaling inhibitors fail to get the ideal effects in cancer treatment." (PMID 31368612, 2019). "A low response rate to anti-EGFR targeted therapy, distinct inter- and intratumoral heterogeneity, relatively aggressive clinical features, and the functional and esthetic importance of head and neck anatomy are features that make HNC a challenging cancer to treat." (PMID 30700700, 2019). "Since HER family members transduce their mitogenic and invasive responses via combinatorial heterodimerization of HERs upon the activation of ligands to EGFR or HER3, cancer cells could manifest a full repertoire of HER signaling without co-overexpression of HER family members." (PMID 31426393, 2019). "The compound-promoted depletion of EGFR resulted in the sequestration of non-phosphorylated Bim, which no longer ensured the integrity of the cytoskeleton machinery, as shown by the detachment of cancer cells from the extracellular matrix (ECM)." (PMID 31374910, 2019). "The SLIT/ROBO pathway has important roles in tumorigenesis, cancer progression and metastasis and thus acts as a regulator for multiple oncogenic signalling pathways including the CD20, mTOR (mammalian target of rapamycin), VEGF and EGFR (epidermal growth factor receptors) pathways." (PMID 30857150, 2019). "With regards to known cancer drivers, 24 showed alterations, including the oral cell lineage transcription factors TP63 (amplified, 21.94%) and SOX2 (amplified, 20.97%), CDKN2A, CCND1 (amplified, 24.27%), PIK3CA (amplified, 20.97%) and EGFR (amplified, 10.67%)." (PMID 31703248, 2019). "However, neither the phosphorylation status nor the expression levels of EGFR in cancer tissues is predictive for efficacy of anti-EGFR mAbs." (PMID 31508364, 2019). "It should be stressed that SNX1 depletion induces a dramatic increase in the expression of phosphorylated form of EGFR in the cancer cell lines studied, whereas no increase of pEGFR was observed in the control siRNA-transfected cells as analyzed by western blotting." (PMID 35582586, 2019).
cancer (continued). "The shift toward KID function of EGFR by TKI in TKI sensitive cancer cells is also supported by the observations that TKIs shift EGFR from non-lipid raft regions to lipid rafts where many cell survival dependent proteins, such as mTORC2, Na+/K+ ATPase, fatty acid synthase reside." (PMID 31508364, 2019). "However, the ability of ORAI3 but not ORAI1 silencing to attenuate EGFR phosphorylation induced by hypoxia suggested that specific events in cancer cells activated by hypoxia are fine-tuned by ORAI3." (PMID 30754719, 2019). "Furthermore, EGFR-TKIs induce autophagy in NSCLC and other cancer cells." (PMID 31196210, 2019). "We then apply NetBiTE to the Genomics of Drug Sensitivity in Cancer (GDSC) dataset and demonstrate that NetBiTE outperforms RF in predicting IC50 drug sensitivity, only for drugs that target membrane receptor pathways (MRPs): RTK, EGFR and IGFR signaling pathways." (PMID 31685861, 2019). "Due to the under- and overexpression of Her4 under different scenarios in cancer, the biological importance of Her4 expression in cancer development is not completely understood and the development of treatments targeting Her4 is not as advanced as for targeting EGFR or Her2." (PMID 31756933, 2019). "Moreover, EGFR, PIK3R1, and PIK3CA are well-known cancer genes." (PMID 31024613, 2019). "Molecular docking studies have demonstrated that derivatives of zerumbone with the presence of amine, epoxyamine, hydroxylamine, and nitrile groups can exhibit potent anti-cancer activities against CCA cells by interacting with the molecular target EGFR, but not CDK-2, CDK-5, and GSK-3." (PMID 30781671, 2019). "Likewise, EGFR inhibitor Gefitinib could affect both ATF4 and MYC expression in EGFR mutant cancer cells and xenograft models." (PMID 31221965, 2019). "It is proposed that targeting the KID pro-survival function of EGFR by reducing its protein levels or interrupting the mechanisms mediating its KID pro-survival function may lead to novel and more effective approaches of targeting EGFR for cancer therapy." (PMID 31508364, 2019). "Indeed, the increased expression of PD-L1 was also observed in epidermal growth factor receptor (EGFR)-resistant tumors, suggesting that the activation of the immune checkpoint may delay the treatment efficacy of TKIs in cancer patients." (PMID 31470510, 2019). "Why do wild-type EGFR expressing/overexpressing cancers not response to EGFR TKIs?" (PMID 31508364, 2019). "Given the apparent wide distribution of EGFR in cancer and non-cancer cells, and its cross-specificity, the level of cancer-specificity that may be achieved through this receptor needs to be critically evaluated." (PMID 29966356, 2018). "Co-targeting EGFR’s KD and KID functions may hold a new promise of treating EGFR-positive cancers." (PMID 29358623, 2018). "Taken together, the TGFα-EGFR-Akt signaling axis can play a role in enhancing proinflammatory chemokine expression in TNBC, subsequently contributing to the inflammatory burden that ultimately lead to cancer progression and a higher mortality rate among TNBC patients." (PMID 30034618, 2018). "Hence, in addition to blockage of EGFR signaling, Cetuximab induces ADCC and the relevance of NK cells and innate immune system in the anti-cancer efficacy of this antibody has gained intense attention, also with respect to design of novel combination strategies." (PMID 30042828, 2018). "Therefore, EGFR downstream proteins, such as signal transducer and activator of transcription 3 (STAT3), play a crucial role in activating Wnt signaling in colon and ovarian cancers." (PMID 30068339, 2018).
cancer (continued). "Since HCC827 cells express EGFR activating mutant, which dominantly controls pro‐survival Akt signal, cigarette smoke may only switch the oncogene addition from the EGFR to MET pathway in wtEGFR‐expressing NSCLC cancer cells." (PMID 29570930, 2018). "For EGFR WT patients, the relationship between MET amplification and PD-L1 expression may be critical for personalized cancer treatment that downregulates the RAS/MAPK pathway and where PD-L1 inhibitors are likely to be effective given the over-expression of PD-L1 seen in this patient population." (PMID 29568386, 2018). "UBASH3B contain an SH3 domains and could promote cancer progression by targeting CBL ubiquitin ligase for dephosphorylation and inactivation, which in turn leads to up-regulation and accumulation of activated EGFR." (PMID 29492198, 2018). "When the cells were treated with a combination of cetuximab and MEK or JNK, the expression levels of CCL5, CXCL9 and CXCL10 increased, confirming that not one but multiple pathways downstream of the EGFR act in concert to block IFNγ/TNFα -induced chemokine expression by these cancer cell lines." (PMID 30192802, 2018). "Importantly, our study represents the first report on ctDNA changes in EGFR‐mutant cancers before and after histological transformation to SCLC and provides important insight into the management of this alterative form of resistance mechanism to EGFR‐TKI." (PMID 29848757, 2018). "Moreover, compound 4g not only exhibited significant cytotoxicity against most of the cancer cell lines, but also showed significant inhibitory activity (IC50 = 40.7 nM) towards EGFR comparable to that of the medicinally important EGFR inhibitor, gefitinib (IC50 = 38.9 nM)." (PMID 30065164, 2018). "Here, we prove the feasibility of assigning genes to cancer pathways by genome-wide forward genetics using genome-edited human cell systems, link FOXO3, NCOA3, and TCF7L2 to phenotypes of the EGFR/Ras/MAPK pathway, and implicate FOXO3 and NCOA3 in the response to anti-EGFR therapy." (PMID 29301589, 2018). "However, because the present data also indicated that the protein expressions of GGA1 and/or GGA3 were also increased in some cancer tissues, relative amounts of GGA1, 2, and 3 could determine the EGFR stability." (PMID 29358589, 2018). "C225 acts as a signaling inhibitor via binding to the accessible extracellular domain of EGFR for blocking EGFR activity and inhibiting the unregulated progression of cell cycle, and has been approved by the FDA (Food and Drug Administration) for the treatment of a variety of EGFR-positive cancers." (PMID 29470420, 2018). "Moreover, a PTEN-null stromal microenvironment likely has similar pro-tumorigenic effects upon residual EGFR/HER2-positive cancer cells from all tissue types that are not eliminated by first-line therapies." (PMID 30018330, 2018). "However, since the cancer-promoting roles of Fas have emerged, only a few studies have touched upon the relationship between Fas and EGFR in cancer and mainly focused on the influence of EGFR signaling on Fas pathway and not vice versa." (PMID 30127519, 2018). "In conclusion, we show PHLDA2 regulation by EGFR/ErbB2 signaling, demonstrate a correlation between PHLDA2 expression, AKT pathway activation and EGFR mutational status and show that PHLDA2 has key negative feedback inhibitory functions in EGFR/ErbB2-driven cancer cells." (PMID 29861842, 2018). "However, that there is a precedent for functional and therapeutically actionable EGFR, MET, and BRAF kinase domain duplications in other cancers is suggestive that a similar mechanism may be applicable to the observed RET kinase duplications in breast cancer." (PMID 30446652, 2018). "To identify novel potential cancer targets whose inhibition is likely to effectively diminish non-responder insusceptibility to β1 integrin and EGFR targeting for radiosensitization, we applied a more restrictive filtering to uncover genes mutated in at least two cell lines." (PMID 29719593, 2018).
cancer (continued). "Furthermore, for even the most responsive cancers, the NSCLC, only those with gain-of-function mutations in EGFR tyrosine kinase activity respond well to TKIs, whereas cancers that express wild-type EGFR either respond poorly, or not at all23." (PMID 29358623, 2018). "The importance of RICTOR downstream of RTK in cancer is highlighted by the fact that not only can alterations of RICTOR and RTK co-occur in some tumors, but also that RICTOR expression is essential to permit the oncogenic potential of RTKs such as HER2, PDGFR, or EGFR." (PMID 29455662, 2018). "Thus, the potentiation of the cytotoxic effects of anti-cancer drugs by dacomitinib in MDR cells was not related to the inhibition of EGFR or Her-2 receptors and their downstream signaling pathways." (PMID 29458405, 2018). "Whilst the use of such cell lines may not be an entirely accurate representation of in vivo cancer cell behavior, these cells provided a good model for studying the effect of such inhibition as they express both endogenously activated EGFR and ERBB4." (PMID 30044378, 2018). "Indeed, according to this model, it appears that FGFR3 is founded in a negative cross-talk from FGFR3 to EGFR, thus indirectly inhibiting the growth factor receptor EGFR, which is also a documented target in cancer therapies." (PMID 29515890, 2018). "The mechanism of AQP5-facilitated cancer cell invasion and metastasis might be due to its direct or indirect interaction with the epidermal growth factor receptor/extracellular signal-regulated kinase (ERK1/2) pathway, known to be important in cancer metastasis and aggressiveness." (PMID 29922644, 2018). "Interestingly, two out of three TNBC samples not expressing EGFR are also Notch3 negative but express Notch1 (case 2), thus reinforcing the relevant Notch3-EGFR direct correlation in this cancer subtype." (PMID 29795369, 2018). "Because EGFR is known to activate NF-κB through a PKC-dependent mechanism, the research group led by Xin Lin sought to investigate whether a CARMA3-containing CBM signaling complex might serve to bridge EGFR stimulation and NF-κB activation in cancer cells." (PMID 30158935, 2018). "Thus, a cross-regulatory role of EGFR and EpCAM appears as a general regulatory mechanism that is instrumental in carcinoma cells and includes negative and positive feedback loops to control ERK1/2 and, ultimately, cell fate." (PMID 30261040, 2018). "In addition, patients ≥75 years with non-squamous EGFR wild-type carcinoma had a tendency to live longer than their younger counterparts (median OS: 7.93 vs 5.16 months; p = 0.2895)." (PMID 29587656, 2018). "Moreover, we analyzed whether leptin-induced proliferative responses in 1321N1 cells involved EGFR or PDGFR, important signaling mechanisms in cancer cells." (PMID 28249041, 2017). "In this respect, here we suggest that the reduction of EGFR on cancer cell membrane, could not allow EGFR hetero-dimerization with MET and, therefore, subsequently block MET transactivation." (PMID 28978055, 2017). "Upon stimulation of ligand, EGFR undergoes homo- or heterodimerization, which leads to autophosphorylation and subsequently turns on several downstream intracellular signaling pathways (including Ras/MAPK, PI3K/Akt, and Jak/STAT) to drive cancer growth and proliferation." (PMID 29238696, 2017). "Tailoring the AAb profiling with a systems biology approach provides an excellent image of the network of AAbs targeting proteins which may be key drivers of cancer-interacting SPs such as PLD, PI3K-Akt, MAPK, EGF/EGFR, c-Met, Ras, DDR, IL-4, IL-6, and TGF-β SPs in the NSCLC and SM groups." (PMID 29062084, 2017). "However, the effect of a hypoxic environment on arginase expression has not been studied in cancer cells, nor has the role of EGFR signaling in hypoxia‐induced arginase expression." (PMID 28330951, 2017).
cancer (continued). "Following pathway analysis of the seven cancer types, we have found ten common cancer – related pathways such as axon guidance, cell cycle checkpoints, signaling by FGFR, DNA repair, DNA replication, opioid signaling, HIV infection, cell cycle, mitotic signaling by NGF, and signaling by EGFR." (PMID 29020948, 2017). "In addition, Western blot analysis also showed that the EGFR expression level and phosphorylation at 1068 were both increased in cells plated at higher cell densities, which were similar to HCT116, CNE-2Z and A549 cancer cells." (PMID 28061454, 2017). "Indeed, some small molecules agents analyzed in this study were mainly multikinase-inhibitors (e.g. vandetanib: EGFR VEGFR RET) or substances (e.g. thalidomide) which affected a lot of cellular processes and antiangiogenesis was only part of anti-cancer mechanisms." (PMID 27901478, 2017). "Dacomitinib did not improve OS compared to erlotinib in patients with EGFR WT cancers." (PMID 28424775, 2017). "Various reports have identified cancer relevant pathways, including the vascular endothelial growth factor (VEGF) receptor, the cyclooxygenase-2 (COX-2), epidermal growth factor receptor (EGFR), and mammalian target of rapamycin (mTOR), as EC treatment targets." (PMID 28881819, 2017). "Here, we focused on lapatinib, which inhibits both HER2 and EGFR and prevents activation of important downstream pathways, such as ERK/MAPK (extracellular-signal-regulated kinase/mitogen-activated protein kinase) and PI3K (phosphatidylinositol 3-kinase) which can drive cancer progression." (PMID 28481952, 2017). "In addition, we found that knockdown of EGFR and CLPTM1L expression significantly inhibited migration and invasion, whereas knockdown of ATP9B or PQLC1 significantly enhanced migration and invasion of cancer cells." (PMID 28548104, 2017). "The PI3K pathway has been described in several studies to regulate glucose metabolism in cancer, thus our findings on inhibitory effects on CXCR4 expression and EGFR activation/expression could be involved in the reduction of glycolytic flux by the inhibition of PI3K/AKT axis." (PMID 28423060, 2017). "In this model, cancer was induced by activating the EGFR/PDGFR and PI3K pathways in glial cells, and the authors found that some neural cell types were not prone to neoplastic transformation, highlighting the relevance of the cell of origin to cancer initiation and progression." (PMID 29445734, 2017). "Indeed, overexpression of miRNA-7 in cells shows significant downregulation of ERBB2 but not EGFR1 in contrast to EGFR being targeted by miRNA 7 in cancer cells suggesting cell specific regulation of miRNA targeting the EGFR receptors." (PMID 28329018, 2017). "Additionally, EGFR, HER2, c-MYC, and MET have been identified to be potential biomarkers that predict the efficacy of the pharmacological treatments targeted against protein products of these genes in various cancers." (PMID 28764718, 2017). "Therefore, it is possible that TMEM16A overexpression may be used to predict therapeutic responses of EGFR/HER2 inhibitors in patients with breast and HNSCC cancers." (PMID 28893247, 2017). "The epidermal growth factor receptor (EGFR) overexpresses and activates the downstream phosphoinositide 3-kinase-AKT and mitogen-activated protein kinase-extracellular signal-regulated kinase (ERK; MEK) signaling pathways, respectively, thus regulating the survival and proliferation of cancer cells." (PMID 28787001, 2017). "Promising data from preclinical studies suggest that CDCP1 targeted agents, including therapeutic antibodies, could be useful in the treatment of cancer patients selected on the basis of activation of CDCP1 and its signaling partners including EGFR, HER2, Met and Src." (PMID 26973855, 2016). "However, no information related to ZNF216 expression compared to EGFR expression in human cancer cell lines was available." (PMID 27732953, 2016).